SEMA6B (semaphorin 6B)
Description:
Functions as a cell surface repellent for mossy fibers of developing neurons in the hippocampus where it plays a role in axon guidance. May function through the PLXNA4 receptor expressed by mossy cell axons. (Microbial infection) Acts as a receptor for P.sordellii toxin TcsL in the in the vascular endothelium.
Synonyms: SEMAN; SEMAZ; SEMA-VIB; SEM-SEMA-Z; EPM11; SEM-SEMA-Y
Tractability: Antibody: UniProt places it where antibodies can reach, with high confidence; UniProt predicts a signal peptide or a membrane-spanning region; its Gene Ontology location is reachable by antibodies, with medium confidence. PROTAC: its protein half-life has been measured.
Gene: Protein-coding gene on chromosome 19 (4,542,588 to 4,581,784, reverse strand). Ensembl gene ENSG00000167680.
Subcellular location: Cell membrane
Gene Ontology:
Molecular function: protein binding; chemorepellent activity; semaphorin receptor binding
Biological process: central nervous system development; axon guidance; hippocampus development; neural crest cell migration; positive regulation of cell migration; semaphorin-plexin signaling pathway; negative chemotaxis
Cellular component: plasma membrane
Genetic constraint (gnomAD): Loss-of-function variants: 47 observed, 72.65 expected, observed/expected ratio (o/e) 0.65, 90% interval 0.51 to 0.82. The synonymous counts are far from expectation, so gnomAD's model fits this gene poorly and the ratio says little. Missense variants: 1,212 observed, 1,070.9 expected, observed/expected ratio (o/e) 1.13, 90% interval 1.08 to 1.19. Synonymous variants: 632 observed, 493.87 expected, observed/expected ratio (o/e) 1.28, 90% interval 1.2 to 1.37.
Gene-disease validity (ClinGen):
ClinGen rates the evidence that SEMA6B causes each of these diseases.
progressive myoclonus epilepsy (autosomal dominant): Definitive. A rare group of disorders characterized by the development of myoclonic and tonic-clonic epileptic seizures associated with progressive degeneration of the nervous system.
Homologues: Orthologues: chimpanzee SEMA6B (99% identical), macaque SEMA6B (98% identical), pig SEMA6B (94% identical), dog SEMA6B (93% identical), mouse Sema6b (89% identical), rat Sema6b (89% identical), guinea pig SEMA6B (71% identical), tropical clawed frog sema6b (53% identical), zebrafish sema6ba (51% identical), zebrafish sema6bb (45% identical). Paralogues in human: SEMA6A (46% identical), SEMA6D (42% identical), SEMA6C (38% identical), SEMA4B (25% identical), SEMA5B (25% identical), SEMA5A (24% identical), SEMA4C (23% identical), SEMA3B (23% identical), SEMA3F (22% identical), SEMA3A (22% identical), SEMA3G (22% identical), SEMA3D (21% identical), and 7 more.
Diseases named in the same sentence as SEMA6B in open-access papers:
SEMA6B is named in the same sentence as 35 diseases in open-access papers, as found by Europe PMC text mining. Sharing a sentence is not in itself a finding about the gene and the disease. The quoted sentences say what the papers report.
breast carcinoma (7 papers, 2021 to 2025). "In contrast to breast cancer, high expression of SEMA6B was assessed in other types of tumors: gastric, gallbladder, and colorectal cancers." (PMID 38067240, 2023). "In breast cancer tissues, the SEMA6B promoter undergoes abnormal methylation, and downregulation of SEMA6B messenger RNA (mRNA) has been found in tumor samples." (PMID 34938771, 2021). "SEMA6B has been demonstrated to have a critical role in the prognosis of various tumors, such as gliomas, breast cancer and testicular cancer." (PMID 34976004, 2021). "Functionally, SEMA6B has been found to exert complex roles in the development and progression of tumors such as breast cancer, glioblastoma, gastric cancer, and testicular cancer." (PMID 34938771, 2021). "In breast cancer, high levels of SEMA6B in human MCF-7 cells exhibit an in vitro invasive capacity, and show potential as a key regulator of tumor progression." (PMID 34938771, 2021). "RXRs also heterodimerize with PPARs to regulate the expression of SEMA6B, a gene highly expressed in breast cancer." (PMID 33898466, 2021). "The SEMA6B gene was strongly downregulated in breast cancer tissues." (PMID 37155149, 2023). "Additionally, fenofibrate may reduce semaphorin 6B protein expression, which typically promotes tumor invasion and metastasis in breast cancer patients." (PMID 39057711, 2024). "However, SEMA6B gene products were strongly downregulated in breast cancer tissues." (PMID 37155149, 2023).
glioblastoma (6 papers, 2021 to 2025). The most malignant astrocytic tumor (WHO grade IV). "Experiments with the PPARα agonist clofibrate and human glioblastoma T98G cells have shown a strong downregulation of SEMA6B gene expression." (PMID 38067240, 2023). "The development of tumors in athymic nude mice from implanted U87MG glioblastoma cells in which plexin-A4 or sema6B expression was silenced is strongly inhibited." (PMID 37627074, 2023). "On the contrary, SEMA6B has been reported to be downregulated in human glioblastoma cells upon prolonged treatment with the anti-tumor action of all-trans retinoic acid (ATRA)." (PMID 34938771, 2021). "However, SEMA6B can induce pro-proliferative signaling to promote cell proliferation in U87MG glioblastoma cells." (PMID 41259456, 2025). "Similarly, silencing SEMA6B/plexin-A4 in U87MG glioblastoma cells diminished tumor-forming abilities." (PMID 38067240, 2023). "In addition, plexin-A4 transduces pro-proliferative signals induced by sema6B in glioblastoma cells." (PMID 37627074, 2023). "SEMA6B expression was decreased in two types of glioblastoma cell lines, and silencing SEMA6B expression could inhibit glioblastoma formation." (PMID 37155149, 2023). "As a result of the intrinsic activity of the SEMA6B–plexin-A4–FGFR1/VEGFR2 axis, endothelial cells (HUVECs) and U87MG glioblastoma cells acquired pro-proliferative stimuli that assembled for pro-angiogenic and pro-tumorigenic signaling in the tumor microenvironment." (PMID 38067240, 2023).
gastric cancer (4 papers, 2021 to 2025). A primary or metastatic malignant neoplasm involving the stomach. "SEMA6B is also associated with tumor differentiation, lymph node metastasis and distant metastasis in gastric cancer." (PMID 33754068, 2021). "Silencing of the axon guidance factor semaphorin 6B gene significantly suppressed adhesion, migration, and invasion of stomach cancer cells in vitro." (PMID 39971899, 2025).
colorectal cancer (3 papers, 2021 to 2023). A primary or metastatic malignant neoplasm that affects the colon or rectum. "A previous study indicated that high SEMA6B levels were associated with adverse prognosis of patients with colorectal cancer." (PMID 37155149, 2023). "The role of SEMA6B in colorectal cancer is similar to its function in THCA described in the present study." (PMID 37155149, 2023). "SEMA6B has also been shown to correlate with tumor invasion and metastasis in GC and to be closely related to the immunosuppressive microenvironment in colorectal cancer." (PMID 36604653, 2023). "Overexpression of SEMA6B indicated poor prognosis in colorectal cancer." (PMID 37155149, 2023). "SEMA6B could be considered as a novel prognostic biomarker for colorectal cancer." (PMID 37155149, 2023). "However, the role of SEMA6B in colorectal cancer (CRC) has remained unclear." (PMID 34938771, 2021).
glioma (3 papers, 2019 to 2022). A benign or malignant brain and spinal cord tumor that arises from glial cells (astrocytes, oligodendrocytes, ependymal cells). "SEMA6B promotes the progression of glioma via activating its cognate receptor plexin A4." (PMID 35269749, 2022).
thyroid cancer (3 papers, 2023). "We found that SEMA6B-siRNA markedly suppressed the invasion, migration, and proliferation of thyroid cancer cells." (PMID 37155149, 2023). "Taken together, these results showed SEMA6B is a potential drug target in the prevention and treatment of thyroid gland cancer." (PMID 38067240, 2023). "A previous study indicated that SEMA6B exerted a tumorigenic effect in thyroid carcinoma partly by activating the Notch signaling pathway." (PMID 37155149, 2023). "Another study aimed at building a prognostic prediction model of thyroid carcinoma employed the pattern of SEMA6B gene expression in these malignant tissues." (PMID 38067240, 2023). "In a real-world experiment, the RT-qPCR results were consistent with the bioinformatic analysis, confirming that ADAMTSL4, DOCK6, FAM111B, and SEMA6B were expressed at higher levels in thyroid cancer cells (p < 0.05), while MRPS10 and PSMB7 were expressed at lower levels (p < 0.05)." (PMID 36761753, 2023). "Under pathological conditions, SEMA6B could be involved in thyroid cancer development." (PMID 38067240, 2023). "The study implied that SEMA6B expression, along with other genes tested (PPBP, GCCR), could be used as a prognostic marker in thyroid carcinoma." (PMID 38067240, 2023).
epilepsy (2 papers, 2021 to 2024). A brain disorder characterized by episodes of abnormally increased neuronal discharge resulting in transient episodes of sensory or motor neurological dysfunction, or psychic dysfunction. "Here we present complementary data showing that novel variants occurring de novo in SEMA6B were found in two unrelated individuals with epilepsy." (PMID 34017830, 2021). "Our results provide further evidence to support the initial findings of SEMA6B being causal to epilepsy and indicate that mediating Semaphorin/Plexin signaling is the potential mechanism of the SEMA6B-related disease." (PMID 34017830, 2021). "Our in vitro studies indicated that SEMA6B causes epilepsy with mediating Semaphorin/Plexin signaling." (PMID 34017830, 2021). "Subjects 25 and 52 had deletions involving FGF12 and SEMA6B, two known genes associated with ASD and epilepsy." (PMID 39769462, 2024). "As one of the members of the semaphorin family, SEMA6B is likely to be involved in the onset of epilepsy." (PMID 34017830, 2021).
melanoma (2 papers, 2021). A malignant, usually aggressive tumor composed of atypical, neoplastic melanocytes. "At protein level, several semaphorins, plexins and neuropilins have been detected in tissue cancer available in the database, including melanoma, except for Sema4A, Sema4F, Sema4G, Sema6B, plexinA4, plexinB3 for which melanoma specimens resulted weakly positive or prevalently negative." (PMID 33858502, 2021).
ovarian carcinoma (2 papers, 2018 to 2021). A malignant neoplasm originating from the surface ovarian epithelium. "Causal network analysis revealed novel pathways suggesting predicted inhibition of ovarian cancer through master regulator ASCL1 and dataset genes DCX, SEMA6B, HEY2, and KCNIP2." (PMID 35052372, 2021).
testicular cancer (2 papers, 2021). A primary or metastatic malignant neoplasm that affects the testis. "Recently, SEMA6B has been shown to exhibit higher expression levels in testicular cancer tissues than in normal tissues and is considered to be a predictor of poor prognosis in patients with testicular germ-cell tumors." (PMID 34938771, 2021).
breast tumor (1 paper, 2023). "In other words, according to in vitro studies and clinical observation, deficiency of SEMA6B (described earlier) and SEMA6D expression are found in breast tumors and coincide with cancer growth, chemoresistance, and recurrence." (PMID 38067240, 2023).
cervical cancer (1 paper, 2025). A primary or metastatic malignant neoplasm involving the cervix. "In order to explore the signalling mechanisms that may be associated with SEMA6B in cervical cancer, we performed differential gene expression analyses comparing SEMA6B high and low expression subgroups, from which we identified 71 significant DEGs." (PMID 40564066, 2025). "Moreover, SEMA6B is identified as a potential prognostic indicator that is associated with both adverse clinical outcomes and immunosuppressive features in cervical cancer." (PMID 40564066, 2025). "In Furthermore, PCR results showed that SEMA6B expression was significantly reduced in cervical cancer cell lines compared to normal cell lines." (PMID 40564066, 2025). "Therefore, future research will aim to experimentally validate the biological functions of NAGS and SEMA6B in cervical cancer." (PMID 40564066, 2025). "This paradoxical pattern suggests that SEMA6B may play a context-dependent role in cervical cancer progression." (PMID 40564066, 2025). "To investigate the biological relevance of genes within the NAGS model, we first analyzed the expression levels of CSF2RB, SEMA6B, and IRF4 in the TCGA cervical cancer dataset." (PMID 40564066, 2025). "The observed enrichment in extracellular matrix–related processes and focal adhesion suggests that SEMA6B may contribute to epithelial–mesenchymal transition (EMT), a key mechanism in cervical cancer invasion and metastasis." (PMID 40564066, 2025).
clear cell renal carcinoma (1 paper, 2023). A malignant epithelial neoplasm of the kidney characterized by the presence of lipid-containing clear cells within a vascular network. "Besides, by further investigating SEMA6B in multiple different malignancies, we also confirmed that SEMA6B high-expression is characteristic not only in THCA but also in clear cell renal carcinoma (KIRC) and stomach adenocarcinoma (STAD)." (PMID 37155149, 2023).
colon cancer (1 paper, 2021). "We conducted SEMA6B knockdown experiments to further confirm the biological role of SEMA6B in two colon cancer cell lines, i.e., HCT116 and LoVo." (PMID 34938771, 2021). "The mRNA level of SEMA6B in different colon cancer cell lines was investigated through CCLE datasets." (PMID 34938771, 2021). "Transwell invasion assay also showed that SEMA6B silencing significantly decreased the degree of invasiveness in both selected colon cancer cell lines." (PMID 34938771, 2021). "RNA interference was performed to silence the expression of SEMA6B to explore its biological roles in the colon cancer cell lines HCT116 and LoVo." (PMID 34938771, 2021). "The results demonstrate that SEMA6B silencing enables a reduction in proliferation, migration and invasion in vitro; meanwhile, the mRNA expression levels of immunosuppressive molecules were also diminished in silenced colon cancer cells by qRT-PCR." (PMID 34938771, 2021). "Moreover, in vitro cell studies validate that overexpress SEMA6B may promote proliferation and metastasis in two colon cancer cell lines, and help to foster an immunosuppressive microenvironment." (PMID 34938771, 2021).
Insulin resistance (1 paper, 2022). Increased resistance towards insulin, that is, diminished effectiveness of insulin in reducing blood glucose levels. "Genes commonly upregulated in the IR-iPSCs when compared to each IS-iPSC group include EGR1 and MFGE8, which were previously associated with insulin resistance, as well as CD74, SEMA6B, SLFN13, TMEM151B, SLC22A17, and AGRN." (PMID 35987697, 2022).
liver failure (1 paper, 2024). A liver disease characterized by the liver losing or has lost all of its function. "To investigate the mechanisms of SEMA6B in liver failure, we employed conventional knockout (SEMA6B-/-) in embryonic C57BL/6 mice." (PMID 39267780, 2024). "Second, Secondly, we used SEMA6B embryonic knockout mice to study the mechanisms of SEMA6B in liver failure due to the limited availability of SEMA6B macrophage- and hepatocyte-specific knockout mice." (PMID 39267780, 2024). "Transcriptome analysis of liver tissue showed that SEMA6B knockout significantly ameliorated the liver failure signature, significantly downregulating inflammation-related pathways." (PMID 39267780, 2024). "Knocking out SEMA6B rescued mice with liver failure by improving liver functions, reducing inflammatory responses, and decreasing hepatocyte apoptosis." (PMID 39267780, 2024). "SEMA6B knockout alleviated LPS/D-gal-induced liver failure, improved liver function, reduced inflammatory responses, and decreased hepatocyte apoptosis." (PMID 39267780, 2024). "Sequencing data from liver tissues indicated that SEMA6B knockout significantly improved the transcriptome profiles of mice with liver failure." (PMID 39267780, 2024). "Administration of synthetic SEMA6B siRNA led to a reduction in inflammatory cytokine levels in mice with liver failure, assessed by qRT-PCR and ELISA." (PMID 39267780, 2024). "Comparison between the SEMA6B-/--LPS/D-gal and SEMA6B+/+-LPS/D-gal groups showed 405/254 (significant up/down) DEGs, indicating SEMA6B knockout significantly altered the gene expression profile in mice with liver failure." (PMID 39267780, 2024).
lung adenocarcinoma (1 paper, 2021). A carcinoma that arises from the lung and is characterized by the presence of malignant glandular epithelial cells. "Interestingly, high SEMA6B expression levels were associated with poor prognosis of OS in lung adenocarcinoma and lung squamous cell carcinoma, while SEMA6B expression had less influence on the prognoses within other types of cancers." (PMID 34938771, 2021).
myoclonic epilepsy (1 paper, 2021). A group of epilepsy syndromes in which myoclonic seizures are a prominent feature. "In conclusion, the present findings confirm that de novo heterozygous variants of SEMA6B underlie an autosomal dominant type of myoclonic epilepsy with variable severity and different response to anti-epileptic treatment." (PMID 34017830, 2021).
Progressive myoclonic epilepsy (1 paper, 2023). "Moreover, SEMA6B gene mutations are a leading factor in the development of SEMA6B-related progressive myoclonic epilepsy (PME-11)." (PMID 38067240, 2023). "The interaction of SEMA6B with plexin-A2 is involved in the process of axon navigation, and associations have also been demonstrated between the occurrence of specific SEMA6B mutations and the presence of progressive myoclonic epilepsy." (PMID 38067240, 2023).
progressive myoclonic epilepsy-11 (1 paper, 2023). "De novo pathogenic variants in SEMA6B were identified to cause progressive myoclonic epilepsy-11 and have also been described as causing RTT-like clinical phenotypes." (PMID 37408271, 2023). "The WES of Patient 8 revealed the presence of a de novo frameshift mutation in the gene SEMA6B, predicted to cause a premature truncated protein (c.1991delG; p.Gly664fsX21; CADD PHRED score: 16.8), and de novo heterozygous mutations in SEMA6b is indicated to cause progressive myoclonic epilepsy-11." (PMID 37408271, 2023).